CRH (corticotropin releasing hormone)
Description:
Hormone that plays a central role in whole body adaptation to stress (By similarity). Released by the hypothalamus primarily in response to physical or psychological stress and acts by binding to CRH receptor CRHR1, and to a lower extent, CRHR2. CRH-dependent signaling is a primary mediator of the neuroendocrine, autonomic (fight-or-flight) and behavioral responses to stress, acting as a key regulator of adaptation by activating the hypothalamus-pituitary-adrenal axis, leading to corticotropin hormone (ACTH) production (By similarity). Acts as a 'placental clock' during pregnancy, regulating gestational length, fetal development and the timing of labor. Also acts as a regulator of blastocyst implantation by promoting decidualization, regulating trophoblast invasion and facilitating maternal immune tolerance.
Synonyms: CRF; CRH1
Tractability: Antibody: its Gene Ontology location is reachable by antibodies, with high confidence; UniProt places it where antibodies can reach, with medium confidence; UniProt predicts a signal peptide or a membrane-spanning region.
Target class: Secreted protein
Gene: Protein-coding gene on chromosome 8 (66,176,376 to 66,178,464, reverse strand). Ensembl gene ENSG00000147571.
Subcellular location: Secreted
Pathways (Reactome):
Signal Transduction: Class B/2 (Secretin family receptors); G alpha (s) signalling events
Gene Ontology:
Molecular function: corticotropin-releasing hormone activity; protein binding; corticotropin-releasing hormone receptor 1 binding; corticotropin-releasing hormone receptor 2 binding; neuropeptide hormone activity; signaling receptor binding; hormone activity
Biological process: female pregnancy; positive regulation of corticotropin secretion; positive regulation of cortisol secretion; regulation of NMDA receptor activity; synaptic transmission, dopaminergic; chemical synaptic transmission; general adaptation syndrome; learning or memory; negative regulation of circadian sleep/wake cycle, REM sleep; neuropeptide signaling pathway; parturition; positive regulation of circadian sleep/wake cycle, wakefulness; signal transduction; social behavior
Cellular component: extracellular region; neuronal cell body; synapse
Genetic constraint (gnomAD): Loss-of-function variants: 6 observed, 6.43 expected, observed/expected ratio (o/e) 0.93, 90% interval 0.51 to 1.72. That is too few expected variants to judge how well the gene tolerates losing a copy. Missense variants: 289 observed, 224.17 expected, observed/expected ratio (o/e) 1.29, 90% interval 1.17 to 1.42. Synonymous variants: 155 observed, 107.22 expected, observed/expected ratio (o/e) 1.45, 90% interval 1.27 to 1.65.
Gene-disease validity (ClinGen):
ClinGen rates the evidence that CRH causes each of these diseases.
epilepsy (autosomal dominant): Refuted. A brain disorder characterized by episodes of abnormally increased neuronal discharge resulting in transient episodes of sensory or motor neurological dysfunction, or psychic dysfunction.
Homologues: Orthologues: chimpanzee CRH (100% identical), macaque CRH (98% identical), dog CRH (88% identical), pig CRH (86% identical), rabbit CRH (85% identical), guinea pig CRH (79% identical), mouse Crh (77% identical), rat Crh (77% identical), zebrafish crhb (41% identical), zebrafish crha (32% identical). Paralogues in human: UCN (21% identical).
Diseases named in the same sentence as CRH in open-access papers:
CRH is named in the same sentence as 310 diseases in open-access papers, as found by Europe PMC text mining. Sharing a sentence is not in itself a finding about the gene and the disease. The quoted sentences say what the papers report.
Anxiety (346 papers, 1998 to 2026). Intense feelings of nervousness, tension, or panic often arise in response to interpersonal stresses. "In relation to emotional regulation, IPA canonical pathway analysis predicted that PLDP negatively impacts corticotropin-releasing hormone signaling, a key regulator of the stress response implicated in mental disorders such as anxiety and depression." (PMID 40436945, 2025). "While some patients are asymptomatic, others present with chronic fatigue, anxiety, depression, and weight loss due to excess CRH [7‐10]." (PMID 39850725, 2025). "Second, CRH neurons are implicated in reward-related behaviors, sleep, anxiety, and depressive-like behaviors." (PMID 40370500, 2025). "The comorbidity of addiction and anxiety suggests common underlying pathological neural circuits, and the vBNST CRH neurons should be critical ones." (PMID 38681523, 2024). "Chronic activation of the CRH system has been associated with various stress-related psychiatric disorders, including anxiety, anorexia nervosa, depression, and PTSD." (PMID 39595978, 2024). "In human depression, CRH–NE hyperactivation of the CRH–NE feed-forward system is implicated in sympathetic activation, hyperarousal, and anxiety." (PMID 38927393, 2024). "Dysregulation of the amygdala–hippocampus axis is linked to stress-related anxiety, with hippocampal neurogenesis being stimulated by antianxiety treatments such as electroshock therapy and corticotropin-releasing hormone (CRH)-1 antagonists." (PMID 39275174, 2024). "CRH is a peptide synthesized by the hypothalamus, associated with functions such as anxiety, emotion, arousal, feeding, sympathetic activity, and immune and cardiovascular regulation." (PMID 38894741, 2024). "The CRH system is associated with serotonergic mediation, emotional imbalance, behavioral changes, anxiety, and depression." (PMID 37998661, 2023). "The very same LC projecting CRH neurons have also been implicated in stress-induced anxiety, despair and aversion." (PMID 37511494, 2023). "The hypothalamus regulates stress and anxiety responses via the corticotropic axis and tanycytes are also known to be morphologically associated with corticotropin releasing hormone (CRH) axon terminals." (PMID 35370973, 2022). "Negative correlation between CeA/CRH SSD and number of hidden marbles in MBT demonstrates both the potent anxiolytic effect of fluoxetine after stress, and that higher CeA/CRH level is associated with lower anxiety." (PMID 36213293, 2022). "The CRH system is long associated with serotonergic mediation, emotional disbalance, behavioral changes, anxiety, and depression." (PMID 36004833, 2022). "Nevertheless, female mice do present a GFRAL-dependent induction of hypothalamic CRH, which has been often been linked to increased anxiety-like behaviors." (PMID 36271504, 2022). "A reciprocal relationship with CRH is suggested, as neurons of both neuropeptides are innervating regions in the limbic system, especially regions associated with anxiety and depression." (PMID 36004833, 2022). "For instance, symptoms for anxiety and depressive disorders have been linked with hypersecretion of corticotropin-releasing hormone (CRH) and high levels of circulating glucocorticoids." (PMID 33867910, 2021). "Disturbance inthe CRH system functioning is associated with the occurrence of addictions, anxiety, post-traumatic stress syndrome, and major depressive disorder." (PMID 34901719, 2021). "In wild-type mice, maternal separation caused a reduction in anxiety-like behavior and in the activation of the hypothalamic paraventricular nucleus, specifically in corticotropin-releasing hormone-positive cells, after the elevated plus maze." (PMID 34895132, 2021).
Anxiety (continued). "The results show a more complex modulating rolefor the CRH system than the conventional wisdom, whereCRHR1 causes anxiety and CRHR2 mediates recovery afterstress." (PMID 34901719, 2021). "Regarding anxiety, high levels of cortisol and CRH (corticotrophin releasing hormone), have been associated to fear states and anxiety-like behavior in experimental models." (PMID 32581876, 2020). "Of particular interest is CRH production in the central nucleus of the amygdala (CeA), where it has been implicated in regulating behavioral responses to anxiety and depression." (PMID 32066677, 2020). "Stress, anxiety, and inflammation cause changes in the expression of genes (GR, CRH, and TRPV1) in brain centers critical for stress reactivity and sensory neurotransmission (amygdala, dorsal horn)." (PMID 35295688, 2020). "Dysregulation of the corticotropin-releasing hormone (CRH) system has been implicated in stress-related psychopathologies such as depression and anxiety." (PMID 31619956, 2019). "Both rodent and human studies have implicated a role for CRH-BP in stress-related psychiatric disorders, including anxiety, depression and addiction." (PMID 29066956, 2017). "Overactive CRH signaling has been implicated in anxiety, major depression, and inflammatory disorders and an effective intervention targeting the CRH signaling pathway is highly sought in these fields." (PMID 28633663, 2017). "In rodent models, increased anxiety-related behavior is associated with greater Crh gene expression in the amygdala and central administration of CRH is able to induce anxiety-like behavior in rats (Dunn and Berridge, 1990, Schulkin, 2006)." (PMID 26318631, 2015). "Key Results Olfactory bulbectomy mice demonstrated chronic depression- and anxiety-like behaviors associated with elevated central CRH expression and increases in c-Fos activity, serotonin levels, and motility in the colon." (PMID 23773726, 2013). "It therefore appears that short term CeA CRH OE results in anxiogenic phenotypes while longer term CeA CRH OE causes a blunting of anxiety behaviors." (PMID 23077729, 2012). "NE and CRH systems in the extended amygdala are implicated in the anxiety response that occurs during withdrawal from long-term opiates, cocaine, ethanol and cannabinoids." (PMID 21869897, 2011). "The dysregulation of brain CRH systems has been implicated in mediating increased anxiety-like behaviors during abused substances withdrawal." (PMID 21869897, 2011). "Behavioural changes in adults exposed prenatally to glucocorticoids appear associated with altered functioning of the amygdala, the key structure involved in the expression of fear and anxiety, with amygdala CRH levels implicated in fear-related behaviours." (PMID 21144857, 2011). "CRH neurotransmission in both of these regions has been implicated in the expression of anxiety-like behaviors, and several studies have reported significantly elevated CSF CRH levels in depressed patients." (PMID 19587852, 2008). "In animals, CRH produces various anxiety-, arousal-, and stress-associated behaviors." (PMID 38927393, 2024). "Moreover, anxiety and depressive disorders are associated with the hypersecretion of corticotropin-releasing hormone, which leads to high levels of circulating endogenous glucocorticoids." (PMID 39737421, 2024). "BST CRH neuron activation may cause both anxiogenic and anxiolytic effects in rodents, and CRH neurons interact with other neuron types to influence anxiety-like responses as well as alcohol and drug–seeking behavior." (PMID 33867924, 2021). "It is concluded that synbiotic nutritional supplements can improve anxiety, stress, and sleep quality, particularly in sportspeople, which appears to be linked to an improved immuno-neuroendocrine response in which IL-1β, CRH, and dopamine are clearly involved." (PMID 33923663, 2021).
Anxiety (continued). "Thus, the current data demonstrate that neonatal pain both acutely elevates amygdalar CRH mRNA and causes a subsequent reduction in anxiety." (PMID 31601633, 2019). "The similarity of the anxiety profile of Ahi1+/+ mice that underwent CUS to the phenotype of Ahi1 deficient mice suggests that chronic stress and Ahi1 deficiency may share a mechanism affecting brain anxiety circuits, such as reduction in amygdalar CRH level." (PMID 29967406, 2018). "Since restraint stress is known to increase CeA CRH and cause anxiety, knockdown of CeA CRH by the viral vector may counteract the effects of stress." (PMID 23077729, 2012). "Extrapolation of these concepts suggests that elevated CRH may be related to anxiety, depression, or other disorders associated with chronic stress responses." (PMID 15606911, 2004). "During alcohol withdrawal, CRH release outside the hypothalamus is enhanced and may cause the anxiety that often occurs in people undergoing withdrawal." (PMID 15706797, 1998). "Alternations in the activity of corticotropin-releasing hormone (CRH) and other neurotransmitters that underlie, increase the anxiety and depressive behavior of the child, indicating that maternal stress hormones may be responsible for the programming of the relevant neural systems of the child." (PMID 35740747, 2022). "Moreover, CRH has been also associated with anxiety and encoding of emotional memories thus highlighting the critical role of the CRH system in the stress response and its role as an important factor in the long-lasting effects of stress, particularly regarding early life stressful experiences." (PMID 32499732, 2020). "The body growth and anxiety phenotypes in lef1 mutants could be explained by reduced expression of multiple hypothalamic genes including crhbp, which encodes a corticotropin-releasing hormone (CRH) inhibitor." (PMID 28837622, 2017). "Therefore, an association between the altered DEX/CRH result and the anxiety scale is reasonable." (PMID 27582123, 2016). "For future studies on pain-mood interaction, one might select additional candidate genes reportedly associated with anxiety and depression; e.g., the genes for corticotropin-releasing hormone (CRH), the adenosine A(2A) receptor, the dopamine D4 receptor, and tryptophan hydroxylase." (PMID 16623937, 2006). "Silencing CRH‐driven anxiety circuits in a mouse model of breast cancer was shown to slow tumor progression." (PMID 41583906, 2026). "While OXT is mainly involved in performing social behaviour, CRH is largely involved in regulating stress and anxiety." (PMID 40559398, 2025). "Corticotropin-releasing hormone (CRH) is a peptide associated with stress and anxiety that acts as a potent modulator throughout the nervous system." (PMID 40830097, 2025). "Recent research suggests that even brief exposure to light at night (0.5-3 hours) can increase levels of corticotropin-releasing hormone (CRH) and cortisol, potentially leading to heightened anxiety." (PMID 40909408, 2025). "The downregulation of calcium activity in CRH neurons in the bed nucleus of the stria terminalis can alleviate anxiety-like behaviors induced by chronic stress." (PMID 39859152, 2025). "Akkermansia muciniphila AM06 (CN116474002A) was shown to modulate the HPA axis by reducing CRH levels and anxiety- and depression-like behaviors in mice treated with 1010 CFU for 56 days." (PMID 40342368, 2025). "First, chronic ATRA treatment induced anxiety- and depression-like behaviors in rats, accompanied by upregulated RARα and CRH expression in the hypothalamus." (PMID 40900922, 2025). "CRHR1 activation by CRH and UCN1 is typically associated with acute stress mobilization and anxiety-like behavior, mirroring VP-mediated HPA axis activation and catabolic mobilization." (PMID 40864786, 2025). "Animal models and human studies have shown that OXT has anti-anxiety effects and CRH induces depression." (PMID 40559398, 2025).
Anxiety (continued). "OXT has a calming effect on the body and reduces anxiety, while CRH activates the HPA axis and helps the body cope with stress." (PMID 40559398, 2025). "Mice with knockout of the hypothalamic corticotropin-releasing hormone (CRH) gene exhibit markedly reduced anxiety-like behavior, demonstrating the paradigm’s sensitivity to drugs and predictive validity." (PMID 41301330, 2025). "According to this model, corticotropin-releasing hormone (CRH)-producing neurons in the BNST selectively target the dorsomedial part of the DR to activate an anxiety- and fear-related subset of serotonergic neurons." (PMID 39766486, 2024). "Central CRH delivery influences functions such as locomotion, arousal, anxiety, reward processing, learning, and memory." (PMID 39596070, 2024). "The paraventricular nucleus of the hypothalamus is commonly activated and the secretion of corticotropin-releasing hormone (CRH) is increased in patients with anxiety and depression." (PMID 39665077, 2024). "The activation of the hypothalamic-pituitary-adrenal (HPA) axis, stimulated by anxiety and depression, results in the release of corticotropin-releasing hormone (CRH) and glucocorticoids." (PMID 38773479, 2024). "CRH is expressed in a variety of anxiety-related extrahypothalamic sites of the central nervous system, including the central amygdala (CeA)." (PMID 37989901, 2024). "This aligns with findings that link heightened CRH activity to several psychopathologies, such as depression, anxiety, PTSD, anorexia, and panic disorder." (PMID 39596070, 2024). "Studies have shown elevated central CRH levels in stress-related anxiety and depressive patients, with normalization observed after treatment." (PMID 39153974, 2024). "Studies have shown that overexpression of CRH in BNST using lentiviral vectors can regulate conditioned anxiety (i.e., persistent fear enhanced startle)." (PMID 38784088, 2024). "Resveratrol at doses 20 and 40 mg/kg decreased anxiety and fear memory in an animal PTSD model that was associated with decreased HPA axis stress hormone levels, including corticosterone, corticotropin-releasing hormone, and adrenocorticotropic hormone." (PMID 39354772, 2024). "Since CRH is associated with depression and anxiety disorders, we performed correlations between anxiety and depression measures and CRH." (PMID 39605973, 2024). "It was reported that anxiety-related CRH + neurons in the CeA project to the LC, and most of the LC neurons that receive projection from the CeA are TH+31." (PMID 37059729, 2023). "Previous animal studies on the effect of SPX on anxiety and depression indicate that it is related to the CRH system, while the CRH system itself is connected to the serotonergic system." (PMID 38255190, 2023). "CRH, released by the bed nucleus of the stria terminalis (BnST), modulates stress-related anxiety via CRHR1 located in the nucleus accumbens and CRHR2." (PMID 37508942, 2023). "Hyperactivity of the HPA axis is a common neuroendocrine finding in affective disorders, and the activation of central CRH pathways is a critical neurobiological substrate of anxiety and depressive states." (PMID 37058223, 2023). "This body of over 9,000 peer-reviewed publications translates into a median support of 9 citations per interaction with the reciprocal relationship between anxiety and the stress hormone CRH being documented in over 400 publications." (PMID 37965360, 2023). "This is in line with the studies showing that increased CRH expression in the brain induces anxiety-like symptoms." (PMID 36661521, 2023). "The ACTH and CRH levels increased significantly in the serum and brain of the rats in the anxiety group, and the serum CORT levels were also significantly higher in these rats." (PMID 37686162, 2023). "For instance, central delivery of CRH results in changes in locomotion, arousal, anxiety, reward, learning and memory." (PMID 37511494, 2023).